BTK (Bruton tyrosine kinase)
Diseases named in the same sentence as BTK in open-access papers (continued):
Sharing a sentence is not in itself a finding about the gene and the disease.
COVID-19 (74 papers, 2020 to 2026). A disease caused by infection with severe acute respiratory syndrome coronavirus 2. "In support, inhibition of BTK in patients with severe COVID-19 has been associated with reduced inflammation and clinical improvement." (PMID 39518015, 2024). "Patients who have received anti-CD20 antibody therapy or BTK inhibitors remain at risk for lower seroconversion whereas those who have been infected with COVID-19 in the past have a very strong immune response likely due to immunologic memory." (PMID 36975207, 2023). "Many of these pathways, including the BTK-dependent activation of NF-B, have been implicated in hyperinflammation during severe COVID-19." (PMID 33791689, 2021). "In particular, monocyte-elevated expression of two key inflammation-associated genes, TLR7 and BTK, is associated with severe outcomes in males with COVID-19." (PMID 34330889, 2021). "Mechanistically, monocyte-elevated expression of Toll-like receptor 7 (TLR7) and Bruton tyrosine kinase (BTK) is associated with severe outcomes in males with COVID-19." (PMID 34330889, 2021). "In particular, the immunomodulatory and anti-inflammatory responses of Bruton tyrosine kinase inhibitors (BTKi), and the potential risks of cytokine storm and hyperviscosity caused by BTKi withdrawal in worsening late complications of COVID-19 are highlighted." (PMID 32803133, 2020). "Acalabrutinib targets activated BTK in macrophages and was associated with reduced inflammation and clinical improvement in COVID-19." (PMID 32503877, 2020). "The mechanisms underlying the activity of BTK inhibitors in improving hypoxia in patients with severe COVID-19 seem to be mediated by an inhibition of exaggerated monocyte autophosphorylation and reduction in interleukin (IL)-6 production." (PMID 32984015, 2020). "While patients treated with anti‐CD20 antibodies, BTK‐inhibitors or anti‐CD38 therapy, often fail to respond and are considered to be at high risk for a severe Covid‐19 disease." (PMID 35602247, 2022). "We identified 230 LUAD/COVID-19 DEGs and constructed a risk score containing 7 genes (BTK, CCL20, FURIN, LDHA, TRPA1, ZIC5, and SDK1) that could classify LUAD patients into two risk groups." (PMID 35733175, 2022). "However, concurrent use of BTK inhibitors in patients who received the COVID-19 vaccine was associated with a markedly reduced response to vaccination." (PMID 36291152, 2022). "On the other hand, BTK inhibitors may cause atrial fibrillation and an increased risk of bleeding and one has to keep in mind that patients with severe COVID-19 often develop severe thrombocytopenia." (PMID 33705648, 2021). "Treon and his colleagues had reported that BTK inhibition could lead to inhibition of cytokine production and potentially decrease the risk of hyperinflammation associated with COVID-19." (PMID 33705648, 2021). "Given BTK’s role in innate immune signaling pathways, inhibitors of BTK are being investigated in treatment of rheumatoid arthritis (RA), and the 2019 novel coronavirus disease (COVID-19) caused by SARS-CoV-2 infection." (PMID 34249912, 2021). "By modulating key transcription factors, BTK may influence macrophage polarization in response to classic M1- and M2-inducing stimuli, potentially mitigating the hyperinflammatory state associated with COVID-19." (PMID 39518015, 2024). "The key role of BTK in the development of ARDS against the background of COVID-19 was shown in the treatment of 19 patients with severe COVID-19 with a selective inhibitor—Acalabrutinib." (PMID 41596367, 2026). "In a preliminary, non-controlled clinical study of 19 patients hospitalized with severe COVID-19, off-label use of the selective BTK inhibitor acalabrutinib improved oxygenation in the majority of patients, often within 1 to 3 d, with no discernible toxicity." (PMID 40461100, 2025).
COVID-19 (continued). "Increased BTK activity also has been reported in CD14+ monocytes from patients with severe COVID-19 compared with those from healthy volunteers, with similar total BTK levels." (PMID 40461100, 2025). "Compared to the HC group, several TPKs in the plasma of PLWH with COVID-19 were significantly downregulated, including BTK, SYK, and TEC." (PMID 40568587, 2025). "Clinically, as reported by us and other investigators, patients with COVID-19–related respiratory distress have shown improved oxygenation following treatment with a BTK inhibitor." (PMID 39906744, 2024). "Lastly, therapeutic targeting of excessive host inflammation by inhibiting Bruton tyrosine kinase (BTK) in severe COVID-19 – for example the BTK-inhibtor Acalabrutinib –was recently described." (PMID 36911878, 2023). "BTK inhibitors were repurposed to tackle COVID-19 due to their modulatory effect on autoimmunity and hyperinflammation." (PMID 36986499, 2023). "Therapeutic strategies for COVID-19 patients are complex, and so the synergistic effects of BTK, FLT3, and EGFR in ALI should also be highlighted in the development of broad-spectrum antiviral compounds that boost the innate response." (PMID 36362264, 2022). "Third, the potential beneficial effect of BTK inhibitors on the amelioration of the COVID-19 clinical course was principally due to the modulation of immunological response, other than through the notable platelet inhibition effect of BTK inhibitors." (PMID 36028857, 2022). "A second study used off-label acalabrutinib (an ibrutinib-like BTK inhibitor) in severe COVID-19 patients which significantly increased the lung function of the patients." (PMID 35626754, 2022). "Recently, the BTK inhibitor baricitinib was approved by the FDA for COVID-19 treatment in combination with remdesivir." (PMID 36362264, 2022). "In our study, 71.4% of the individuals with COVID-19 in their history were receiving BTK inhibitors." (PMID 36613860, 2022). "BTK, a tyrosine kinase, was identified as a top male-biased gene in monocytes of severe COVID-19 patients." (PMID 34330889, 2021). "Altogether, these observations emphasize that sex is a key biological variable in predicting the efficacy of pharmacologic treatments (such as BTK inhibitors) in people diagnosed with COVID-19." (PMID 34330889, 2021). "This proved that BTK inhibitors are relevant for targeting excessive host inflammation in COVID-19 patients." (PMID 34063231, 2021). "Mechanistically, elevated levels of BTK activity have been reported in blood monocytes from patients with severe COVID-19 compared with those from healthy volunteers." (PMID 34778053, 2021). "Currently, two clinical trials are underway to evaluate the efficacy of BTK inhibitors during COVID-19 treatment (NCT numbers: NCT04382586, NCT04346199, ClinicalTrials.gov)." (PMID 34249912, 2021). "Notwithstanding the presently narrow clinical indications of BTKinibs, the connectedness of factors affected by severe COVID-19 and BTK signaling makes BTKinibs attractive therapeutic candidates for patients with severe SARS-CoV-2 infection." (PMID 33791689, 2021). "Kinase inhibitors (like BTK) are beneficial regulators of life-threatening symptoms of COVID-19, including anti-inflammatory, cytokine suppression and antifibrotic activity." (PMID 34209188, 2021). "Severe COVID-19 patient monocytes have significantly elevated BTK phosphorylation compared to healthy volunteers." (PMID 33791689, 2021). "Based on this rationale, the covalent inhibitor of BTK acalbrutinib has been used in a small open-label trial of 19 patients with severe COVID-19 demonstrating some degree of clinical success as well as ex vivo evidence of elevated BTK activity." (PMID 34056149, 2021). "Clinical trials are under evaluation to gain insights into the role of BTK inhibition in improving COVID-19 by reducing the levels and effects of IL-6." (PMID 34001144, 2021).
COVID-19 (continued). "By analyzing gene expression profiles of 838 subjects from the GETx,33 we found an eQTL SNP (rs2071223) on BTK in male-derived lymphocytes (p = 0.005), further supporting the male-specific role of BTK in COVID-19." (PMID 34330889, 2021). "Acalabrutinib, another BTK inhibitor, was also successful in the treatment of several patients suffering from severe cases of COVID-19." (PMID 34063231, 2021). "Some anticancer drugs like cytokine inhibitors, immune checkpoint inhibitors, Bruton tyrosine kinase inhibitors, and hormonal therapy can be repurposed for combating the deadly duo of COVID-19 and cancer." (PMID 33912588, 2021). "In other reports, the effect of blocking BTK in the context of thromboinflammation in COVID-19 is considered." (PMID 34249912, 2021). "BTK is a known regulator of macrophage activation, and treatment of COVID-19 patients with acalabrutinib has been shown to improve oxygenation as well as normalization of IL-6 levels." (PMID 33467724, 2021). "A Bruton tyrosine kinase (BTK) inhibitor, that blocks BTK-mediated signaling and activation of the macrophage, was used to treat patients with COVID-19 with promising results as a potential therapeutic strategy." (PMID 32854247, 2020). "In an effort to reduce inflammation and improve clinical outcome of patients with severe COVID-19, we administered acalabrutinib, a highly specific covalent inhibitor of BTK approved in the United States for the treatment of lymphoid malignancies." (PMID 32503877, 2020). "In accordance with World Health Organizations guidance, we prospectively administered acalabrutinib off-label with therapeutic intent to 19 hospitalized patients with severe COVID-19, based on the known role of BTK in innate immune cells." (PMID 32503877, 2020). "Ex vivo analysis revealed significantly elevated BTK activity, as evidenced by autophosphorylation, and increased IL-6 production in blood monocytes from patients with severe COVID-19 compared with blood monocytes from healthy volunteers." (PMID 32503877, 2020). "Acalabrutinib, a selective BTK inhibitor, was administered off-label to 19 patients hospitalized with severe COVID-19 (11 on supplemental oxygen; 8 on mechanical ventilation), 18 of whom had increasing oxygen requirements at baseline." (PMID 32503877, 2020). "Recent findings demonstrate a possible role for the BTK inhibitor acalabrutinib in treating excessive inflammation in the context of severe COVID-19." (PMID 33226337, 2020). "This prospective study of patients with severe COVID-19 highlights the potential benefit of BTK inhibition and has led to a confirmatory international prospective randomized controlled clinical trial." (PMID 32503877, 2020). "Our clinical and correlative laboratory studies have revealed that BTK is a likely instigator of the pathological inflammatory response in severe COVID-19." (PMID 32503877, 2020). "We observed a significantly increased mean fluorescence intensity of phosphorylated BTK in CD14+ monocytes from patients with severe COVID-19 relative to that observed in healthy volunteers, an increase that was not due to differential levels of total BTK." (PMID 32503877, 2020). "Blocking Bruton tyrosine kinase (BTK) is a proposed mechanism to suppress macrophage activation and is currently being tested in clinical trials of COVID-19 subjects (Acalabrutinib, NCT04380688)." (PMID 32922297, 2020). "Ex vivo analysis of blood samples from patients with severe COVID-19 revealed BTK activation in monocytes in all cases, as evidenced by significantly increased BTK phosphorylation compared with monocytes from healthy volunteers." (PMID 32503877, 2020). "The use of BTK inhibitors in patients with COVID-19 has previously been reported." (PMID 40461100, 2025).
COVID-19 (continued). "Bruton tyrosine kinase (BTK) inhibitors are candidate therapies for COVID-19 as BTK is a critical mediator of B-cell receptor signaling and adaptive immunity and plays a key role in numerous immunologic signaling networks associated with innate immunity (eg, toll-like receptor [TLR] signaling)." (PMID 40461100, 2025). "A past study reported that the BTK inhibitor ibrutinib may provide protection against lung injury in patients with COVID-19 because it reduces proinflammatory and chemoattractant cytokines." (PMID 39834945, 2024). "COVID-19 patients with severe lung inflammation showed aberrant BTK activity." (PMID 36986499, 2023). "BTK inhibitors, which target a wide range of proinflammatory signaling pathways, may play a key role in the management of COVID-19." (PMID 36676732, 2023). "As BTK regulates the activity of macrophages, it has been suggested that BTK inhibitors may have a therapeutic role in COVID-19 patients." (PMID 35159041, 2022). "Inhibition of Bruton tyrosine kinase, a regulator of B-cell maturation 36, could be another viable therapeutic strategy to improve clinical outcomes of COVID-19 patients." (PMID 36263161, 2022). "Ibrutinib, a first-generation BTK inhibitor that effectively inhibits B cell receptor and NFκB signal transduction, which may be beneficial to COVID-19 patients in pulmonary distress." (PMID 36362264, 2022). "Recent clinical trials reported that the use of Bruton’s tyrosine kinase (BTK) inhibitors to treat COVID-19 patients could reduce dyspnea and hypoxia, thromboinflammation, hypercoagulability and improve oxygenation." (PMID 34209188, 2021). "BTK inhibitors are also considered for use in COVID-19 treatment." (PMID 34446699, 2021). "However, data of these drugs is insufficient to evaluate the efficacy and safety in treating COVID-19.279,280 Hence, BTK inhibitors are recommended against COVID-19, except in a clinical trial (AIII)." (PMID 34446699, 2021). "We then speculated on a possible harmful role of B cells in COVID-19 pathogenesis and our hypothesis was further supported by the demonstration that patients under BTK inhibitors also had a mild COVID-19." (PMID 33889552, 2021). "The results identified pathways associated with regulation of inflammation (MAPK14) and immunity (BTK, MBX) that may contribute to exacerbate organ damage linked with complications of COVID-19." (PMID 34907210, 2021). "The promising clinical data of ibrutinib and acalabrutinib at inhibiting cytokine storm and improving lymphopenia in COVID-19 patients will likely promote further development of additional trials to expand the use of BTK inhibitors to sepsis and other infectious and inflammatory diseases." (PMID 34778053, 2021). "and others discussed the potential that BTK inhibition may have in treating the novel virus SARS-CoV-2 (COVID-19)." (PMID 33818636, 2021). "Altogether, monocyte-specific expression of TLR7 and BTK may provide potential explanations for the male-biased disease severity in COVID-19." (PMID 34330889, 2021). "Accordingly, BTK inhibitors may regulate inflammatory responses in COVID-19 by reducing the levels of IL-6." (PMID 34001144, 2021). "Moreover, as the SARS-CoV-2 virus spreads throughout the population, the number of patients already being treated with a BTK inhibitor that contract COVID-19 has increased." (PMID 34249912, 2021). "TLR7 and BTK are male-biased genes in peripheral monocytes with severe COVID-19." (PMID 34330889, 2021). "Inhibiting BTK has been hypothesized to ameliorate lung injury in patients with severe coronavirus disease 2019 (COVID-19)." (PMID 33791689, 2021). "Increase in monocyte BTK activation was found during severe COVID-19 infection and BTK inhibitors could potentially be used to treat severe COVID-19 related inflammation and lung injury." (PMID 34565453, 2021). "Indeed, blood monocytes from patients with severe COVID-19 showed increased BTK activation and production of interleukin-6 correlating with systemic inflammation." (PMID 33791689, 2021).
COVID-19 (continued). "In this context the potential benefits of early phase trials using BTK inhibitors or ruxolitinib in severe COVID-19 patients can be hypothesized to be related to overlapping target specificity and regulation of inflammatory pathways." (PMID 32824276, 2020). "BTK is also a target in other diseases such as allergies or asthma and even COVID-19." (PMID 33226337, 2020). "A more complete understanding how BTK inhibitors modulate the immune pathophysiology of COVID-19 will require the use of preclinical model systems in concert with detailed immune profiling of patients with COVID-19, before and during treatment with a BTK inhibitor." (PMID 32503877, 2020). "To examine whether the target of acalabrutinib, BTK, was activated in patients with COVID-19, we studied BTK autophosphorylation at residue Y223 in whole blood samples from 3 patients with severe COVID-19 and in 5 healthy volunteers." (PMID 32503877, 2020). "If BTK inhibition is of clinical benefit in severe COVID-19, as is supported by our data, it raises the question of which BTK inhibitor would be optimal in this clinical setting given the association of COVID-19 with arrythmias and other serious systemic sequelae of the inflammatory process." (PMID 32503877, 2020). "Our laboratory studies of ex vivo blood samples from patients hospitalized with COVID-19 revealed significantly elevated BTK phosphorylation in peripheral blood monocytes compared with healthy volunteers, demonstrating that the target of acalabrutinib is activated in these innate immune cells." (PMID 32503877, 2020). "In conclusion, available data suggest that the immunomodulatory intervention may be the vital key in the treatment of excessive inflammation during COVID-19 and BTK may be a promising drug target to control severe lung injury in this context." (PMID 33262793, 2020). "Future development of BTK inhibitors will need to consider long-range allosteric consequences of inhibitor binding, including the emerging application of these BTK inhibitors in treating COVID-19." (PMID 33226337, 2020). "Consequently, BTK inhibition in patients with COVID-19 has been a topic of interest." (PMID 39518015, 2024). "Furthermore, one clinical study utilized the BTK inhibitor acalabrutinib in COVID-19 patients." (PMID 33818636, 2021). "Thus, ACE2, TMPRSS2 and BTK were also selected as drug targets for COVID-19." (PMID 34209188, 2021). "Given the activation of BTK and production of IL-6 that we detected in COVID-19 monocytes, we propose that BTK inhibitors target pathological monocyte/macrophage activation and dampen the cytokine storm, which consequently may improve outcomes in these patients." (PMID 32503877, 2020). "Though we expected that the optimal time to initiate anti-inflammatory treatment would be prior to deterioration requiring intubation, these results suggest that BTK inhibition may provide significant benefit to a subset of patients with COVID-19 on ventilators." (PMID 32503877, 2020). "Although we have focused our model on macrophages, BTK is also known to control signaling in neutrophils, megakaryocytes, and platelets, which may also contribute to the immunopathology of severe COVID-19 and be kept in check by BTK inhibitors." (PMID 32503877, 2020). "Consequently, clinical trials to assess the use of BTK inhibitors against COVID-19 are underway." (PMID 32903476, 2020). "A poor response to the COVID-19 vaccination has been observed in patients with CLL and WM receiving BTK inhibitors, although as many as half of patients with CLL and WM who were treatment-naive also lacked serological response to vaccination." (PMID 39906744, 2024). "Interestingly, one study in waldenstrom macroglobulinemia patients with newly diagnosed COVID-19 found that oral ibrutinib at a regular 420 mg d−1 dosing improved oxygenation and decreased inflammatory cytokines of patients, implicating a pro-inflammatory role of BTK in COVID-19." (PMID 36182930, 2022).